IL6 (interleukin 6)
Diseases named in the same sentence as IL6 in open-access papers (continued):
Sharing a sentence is not in itself a finding about the gene and the disease.
sarcopenia (continued). "Specifically, IL-6 and TNF-α high concentrations have been directly related to the process of sarcopenia and frailty in both humans and rats." (PMID 34336096, 2021). "Inflammatory markers including interleukin 6 (IL-6), C Reactive Protein (CRP) and tumor necrosis factor-alpha (TNF-a) were shown to positively correlate with sarcopenia." (PMID 33902634, 2021). "Accumulating evidence demonstrated that the serum levels of tumor necrosis factor (TNF)-α, interleukin (IL)-6, and C-reactive protein (CRP) are elevated in sarcopenia, typically up to 2–4-fold higher than those in young controls." (PMID 32498474, 2020). "Based on the collective results, IL-6, SPARC, MIF and IGF-1 were selected for analysis as potential biomarkers for sarcopenia." (PMID 29872072, 2018). "According to the concept of “inflamm-aging (inflammation +aging)”, inflammatory cytokines, including IL-6, may be involved in age-related diseases, such as atherosclerosis, dementia, type 2 diabetes and osteoporosis, and inflamm-aging might also be involved in sarcopenia." (PMID 29351340, 2018). "The emergence of sarcopenia was accompanied by increased levels of inflammation factors TNF-α and IL-6." (PMID 28701179, 2017). "IL-6 and TNF-α levels in the Sarcopenia group were higher than the control group; the comparison between groups showed significant difference (P < 0.05)." (PMID 28701179, 2017). "Our research results indicated that IL-6 and TNF-α serum levels in elderly subjects with sarcopenia were higher than levels in the control group, and BMI VFA were independent risk factors for inflammatory cytokines IL-6 by multiple regression analysis." (PMID 28701179, 2017). "Taken together, IL-6 and IGF-1 are extremely important regulators of bone and muscle metabolism, which makes them interesting targets for the treatment of osteopenia or sarcopenia." (PMID 25712618, 2015). "Objective radiological assessment of sarcopenia may contribute here, while serum metabolomic markers, TNF‐alpha, IL‐6 and neutrophil–lymphocyte ratio may have a role." (PMID 40781491, 2026). "Previous literature has reported that the mechanism of IL-6 and TNF-α induced sarcopenia may have the following aspects." (PMID 40265008, 2025). "Interleukin-6 (IL-6), also examined in two manuscripts, had a median value of 3.8 [3.3–4.4] pg/mL, but was not correlated with sarcopenia in KTRs." (PMID 41464844, 2025). "For the models of E-DII and inflammatory mediators, AUC measurements for E-DII + cfDNA (AUC = 0.805) were considered a good discrimination, and the evaluation was as acceptable for cytokines IL-1β, IL-6, TNFα and CRP (0.7 < AUC < 0.8) i.e., it enabled sarcopenia diagnosis." (PMID 41345186, 2025). "Emerging evidence suggests that low-grade chronic inflammation—reflected by markers such as IL-6 and CRP—may contribute to the link between oral health and systemic conditions like frailty and sarcopenia." (PMID 40142799, 2025). "In multivariate analysis, high IL‐6 as an independent predictor for sarcopenia was not quite statistically significant (OR 1.84, 95%CI 0.93–3.65, p = 0.08)." (PMID 41380167, 2025). "Moreover, inflammatory cytokines such as TNF-α and IL-6, which are elevated in both T2DM and sarcopenia, have been shown to suppress mitochondrial function by inhibiting PGC-1α and inducing mitochondrial damage." (PMID 40869253, 2025). "Additionally, pro-inflammatory cytokines like interleukin-6 (IL-6) and tumor necrosis factor-α (TNF-α) are elevated in both sarcopenia and OSA." (PMID 40055243, 2025). "The interplay between IL‐6, GDF‐15 and sarcopenia suggests a complex network of inflammatory and metabolic processes that may act synergistically to worsen outcomes in patients with BC." (PMID 41380167, 2025).
sarcopenia (continued). "A randomized controlled study demonstrated that modified Buzhong Yiqi Decoction combined with conventional intervention significantly reduced serum levels of IL-6 and TNF-α in elderly patients with sarcopenia after 2 months of treatment compared to conventional intervention alone (P < 0.05)." (PMID 40661078, 2025). "The dependent variable (sarcopenia) was a binary classification (0= absent, 1= present), and continuous independent variables included levels of four inflammatory cytokines: IL-2, IL-6, IL-8, and TNF-α." (PMID 40265008, 2025). "After categorising patients into groups by the presence of IL‐6 or GDF‐15 and sarcopenia, significant differences in OS and CSS could be shown between these groups (log‐rank in all cases p < 0.01)." (PMID 41380167, 2025). "Therefore, we were able to identify high‐risk patient groups prior to cystectomy by determining serum IL‐6, serum GDF‐15 and sarcopenia." (PMID 41380167, 2025). "Higher IL‐6 serum levels were found in patients with sarcopenia, opposed to patients without sarcopenia (p = 0.04)." (PMID 41380167, 2025). "In sarcopenia, the major pro-inflammatory cytokines include TNF-α, IL-6, and interleukin-1 (IL-1)." (PMID 39582665, 2024). "ROC analysis suggested a good diagnostic yield of myostatin (AUC 0.79), IL-6 (AUC 0.67), and irisin (AUC 0.62) among dialysis patients (KTR were not included due to the very low prevalence of sarcopenia)." (PMID 39125361, 2024). "Consistent with this, we observed significantly higher values of inflammation markers, particularly tripled values of CRP and almost doubled values of IL-6, in sarcopenic obese subjects compared to the group of obese patients without sarcopenia." (PMID 38921440, 2024). "The best self-standing biomarkers of sarcopenia in dialysis patients were myostatin (AUC 0.789) and IL-6 (AUC 0.67); however, the latter was not retained in the final model." (PMID 39125361, 2024). "Notably, cancer-induced hyperuricemia, hyperkaliemia, acute kidney injury (AKI), anorexia, sarcopenia, and high systemic levels of TNF-α, IL-1β, IL-6, and IL-18 can impair heart function, induce myocardial fibrosis and cardiomyocyte atrophy." (PMID 39200115, 2024). "Furthermore, elevated concentrations of TNF-α, IL-6 and CRP are frequently identified in sarcopenia patients These cytokines probably trigger the activation of the ubiquitin-protease system and develop sarcopenia." (PMID 37932727, 2023). "For example, platelet activating factor (PAF), interleukin-6 (IL-6), or tumor necrosis factor-a (TNF-α) can increase muscle breakdown and reduce protein synthesis, while in cachexia and sarcopenia, the inflammatory burden is increased, implying a bi-directional relationship." (PMID 37630805, 2023). "IL-6, as demonstrated by the logistic regression and multicollinearity model, could be considered a marker of cirrhotic HCC-related sarcopenia, suggesting further investigation with BIA- or CT-dedicated software." (PMID 37173873, 2023). "In our study, we noted lower values of inflammatory markers (CRP, CRP/albumin ratio, TNFα, IL-6, IL-1β, cfDNA) in the no-sarcopenia group, as opposed to the sarcopenia group." (PMID 37465171, 2023). "Surprisingly, we did not detect any significant differences in IL-6 concentration between sarcopenic and non-sarcopenic groups either, although a significant role of IL-6 in sarcopenia has already been reported by a large number of studies." (PMID 37465171, 2023). "Indeed, previous studies reported increased levels of IL-6 and TNF, but also higher IL-4 and IL-10, in patients with sarcopenia with respect to healthy individuals." (PMID 38001845, 2023). "From our data, we believe that IL-6 could be useful to detect HCC, especially in case of tumor infiltration, and possibly sarcopenia in all stages of cirrhosis (CP classes A, B or C)." (PMID 37173873, 2023). "Furthermore, the group diagnosed with sarcopenia had a significant increase in systemic inflammatory markers, including CRP and IL-6." (PMID 38026977, 2023).
sarcopenia (continued). "Therefore, our study included ND-CKD patients alone and evaluated sarcopenia as a hard outcome; sarcopenia components including muscle mass index, strength, and physical performance; and inflammatory indicators including hs-CRP, TNF-α, and interleukin-6." (PMID 36566275, 2022). "Higher IL-6, IL-17A, and TNF-α levels were observed in participants with sarcopenia (P < 0.05)." (PMID 35237317, 2022). "Interestingly, inflammation and mDAMPs synergistically contribute to sarcopenia; for example, mDAMPs can activate the Toll-like receptor (TLR) pathway and trigger NF-κB signaling, thus increasing the expression of IL-6 and TNF-α." (PMID 35954203, 2022). "Nonetheless, elderly patients with Chronic Obstructive Pulmonary Disease diagnosed with sarcopenia presented high levels of IL-6 but not IL-10." (PMID 36499366, 2022). "Elevated concentrations of IL-6 and CRP are often detected in sarcopenia and SO." (PMID 35100595, 2022). "People with sarcopenia have higher levels of IL-6, IL-10, and visceral adipose tissue than people without sarcopenia." (PMID 35250869, 2022). "After adjustment for age, sex and BMI, increased concentrations of homocysteine (OR: 2.844; 95% CI, 1.071–7.553) and hs-CRP (OR: 1.021; 95% CI, 1.000–1.042) were independent predictors of sarcopenia but not IL-6." (PMID 34911470, 2021). "Additionally, chronic inflammation has been also considered to be involved in the development of sarcopenia, due to the production of numerous pro-inflammatory cytokines, such as TNF and IL-6, which promote muscle catabolism." (PMID 34680417, 2021). "The average levels of the four proinflammatory cytokines, including IL-1β, IL-6, IL-15, and TNF-α, were significantly increased in sarcopenia patients compared to those in young/healthy volunteers, while the concentrations of two other cytokines, IL-4 and IL-13, were not changed." (PMID 32226296, 2020). "Several biomarkers potentially involved in the development of sarcopenia such as tissue growth factor (TGF)-β and interleukin (IL)-6 are considered as factors that might impair tumour response to immune checkpoint inhibitors." (PMID 30792455, 2019). "A previous study reported that older individuals with sarcopenia had higher levels of serum interleukin (IL)-6 than those without sarcopenia." (PMID 31077169, 2019). "Because increases of IL6, TNFα, and MCP1 were reported as biomarkers and reasons for age-related inflammation and sarcopenia, IL10 could reduce these pro-inflammatory cytokines and mitigate age-related inflammation and sarcopenia." (PMID 30696799, 2019). "The contribution of interleukin-6 (IL-6) to sarcopenia has been suggested based on a negative correlation between plasma IL-6 and muscle function described by some studies." (PMID 29739343, 2018). "The plasma level for IL-6 correlates negatively and reportedly in a nonlinear fashion with muscle strength; thus it is a potential biomarker of sarcopenia." (PMID 29739343, 2018). "Epidemiological studies have reported that IL-6 is strongly associated with functional disability and loss of muscle mass but experimental studies have not been able to link IL-6 to sarcopenia." (PMID 15904534, 2005). "Aging-related sarcopenia is driven in part by chronic low grade systemic inflammation that has been named "inflamm-aging", and that is characterized by elevated pro-inflammatory cytokines such as TNF-α and IL‐6, which contribute to muscle catabolism and mitochondrial dysfunction." (PMID 40821925, 2025). "Indeed, while IL-6 release in response to exercise appears to promote muscle anabolism and reduce circulating TNF-α levels, in the context of sarcopenia, a chronic low-grade inflammatory environment is established in which IL-6 exerts pro-inflammatory effects and promotes muscle catabolism." (PMID 40564069, 2025).
sarcopenia (continued). "The use of more sensitive inflammatory markers, such as IL-6 and TNF-α, may improve the characterization of systemic inflammation in low pSMI individuals and clarify the limited discriminatory capacity of hs-CRP in sarcopenia." (PMID 40909453, 2025). "This could explain the simultaneous increase in IL-6 and TNFα in patients with sarcopenia and probable sarcopenia compared with non-sarcopenia individuals." (PMID 41345186, 2025). "Furthermore, the study did not include circulating biomarkers commonly implicated in sarcopenia and cardiac cachexia, such as TNF-α, IL-6, or myostatin." (PMID 40566033, 2025). "It was found that IL-6 is not an independent factor in sarcopenia." (PMID 40969368, 2025). "Similarly, we found higher serum IL‐6 values in patients with sarcopenia opposed to those without (p = 0.04)." (PMID 41380167, 2025). "Although the baseline levels of serum albumin, C-reactive protein (CRP), and interleukin 6 (IL-6) were comparable between patients with and without sarcopenia, the development of sarcopenia was significantly associated with lower albumin levels and higher CRP and IL-6 levels." (PMID 38797769, 2024). "Additionally, sarcopenia and MDD show a direct relationship to a large extent due to the immunoinflammatory alterations they share, such as elevated levels of IL-6, CRP and TNF-α, responsible for the induction of numerous systemic changes observed in patients with sarcopenia and MDD." (PMID 39681901, 2024). "Third, data on inflammatory markers (eg,C-reactive protein (CRP), interleukin-6 (IL-6)) were not available while these markers mightcorrelate with the body inflammatory status and sarcopenia." (PMID 38885304, 2024). "On the other hand, genetic factors reported as sarcopenia biomarkers have also been identified such as angiotensin I-converting enzyme I (ACE), myostatin (MSTN), alpha actinin 3 (ACTN3), ciliary neurotrophic factor (CNTF), vitamin D receptor (VDR), insulin-like growth factor 1 (IGF1), and IL-6." (PMID 39194921, 2024). "No specific drug therapy for sarcopenia has been established; since inflammatory cytokines such as TNFα and IL-6 produce muscle atrophy, biological agents such as TNF and IL-6 inhibitors used to treat RA may improve sarcopenia in patients with RA, but the evidence is currently limited." (PMID 37041556, 2023). "Interleukin 6 (IL-6) promotes the growth of the HCC microenvironment and could promote sarcopenia." (PMID 37173873, 2023). "The lack of a cirrhotic control group to clarify the role of IL-6 in predicting sarcopenia in this context alone could also be considered a limitation." (PMID 37173873, 2023). "Thus, both skeletal muscle and cognitive functions are affected by chronic inflammation in vivo, and elevated levels of pro-inflammatory cytokines (IL-6 and TNF-α) and decreased levels of anti-inflammatory cytokines (IL-10) may contribute to sarcopenia and CI." (PMID 37962457, 2023). "High levels of pro-inflammatory factors interleukin-6 (IL-6), tumor necrosis factor-α (TNF-α), and C-reactive protein (CRP) may induce sarcopenia by affecting protein balance synthesis, and dysregulation of the inflammation may also be involved in the pathophysiological mechanisms of MCI." (PMID 38148730, 2023). "In addition, elevated IL-6 and IL-17 were detected in elderly patients with sarcopenia and an impaired metabolism, as compared with non-sarcopenic elderly persons." (PMID 35563026, 2022). "In patients undergoing maintenance hemodialysis (MHD), circulating mtDNA contents were significantly higher in sarcopenia patients, together with higher TLR9 and IL-6 expression, which demonstrated that mtDNA could be involved in the pathogenesis of MHD-related sarcopenia." (PMID 36499488, 2022). "In addition, both IS and LPS induce inflammatory cytokine expression (IL-6 and TNF-α) which in turn may sustain sarcopenia." (PMID 33804536, 2021).
sarcopenia (continued). "Compared with the HF group, the expression of IL-6 (P < 0.05) and TNF-α (P < 0.0001) in the HF + levosimendan group was significantly decreased, and the inflammation level of the HF + sarcopenia group was effectively improved after injection of levosimendan (P < 0.0001)." (PMID 35126176, 2021). "The current study showed that higher levels of systemic inflammation (as indexed by CRP) were associated with sarcopenic obesity, which is supported by a recent meta-analysis that showed that sarcopenia is associated with higher CRP, but not with higher IL-6 or TNFα." (PMID 33853546, 2021). "Moreover, cross sectional studies have suggested the increase of IL-6 and TNF-a in sarcopenia." (PMID 34493690, 2021). "Furthermore, some circulating biomarkers of sarcopenia, such as the C-reactive protein and interleukin 6, were not considered in this study." (PMID 35083235, 2021). "Several recent studies have identified inflammatory mediators, such as IL-1, IL-6, and Tumor Necrosis Factor (TNF)-α, as contributing to the development of sarcopenia, since they may induce muscle atrophy promoting protein degradation and reactive oxygen species (ROS) accumulation." (PMID 29462978, 2018). "Elevation of inflammatory proteins, such as interleukin (IL)-6 and tumor necrosis factor alpha (TNF-α), may lead to various physical changes, including a decrease in muscle mass and adipose tissue in patients with sarcopenia." (PMID 28359307, 2017). "However, when analysing non-CKD-related sarcopenia, researchers have noted higher IL-6 levels." (PMID 39126043, 2024). "Moreover, IL-6 levels are also greater in patients with sarcopenia than in those without." (PMID 39597037, 2024). "Moreover, IL-6 emerges for the first time as a potential specific marker of sarcopenia in HCC cirrhotic patients, which is useful especially when other diagnostic tools for detecting early stages of sarcopenia are not available." (PMID 37173873, 2023). "High levels of circulating pro-inflammatory cytokines (CRP, IL-6, TNF-α, etc.)have been found to correlate with low lower handgrip, decreased appendicular muscle mass and reduced knee-extension strength, indicating that these cytokines could be potential biomarkers of sarcopenia." (PMID 36499366, 2022). "Moreover, we did not observe any association between IL-6 and TNF-α and presence of sarcopenia neither before (OR 0.90; 95% CI 0.25, 3.13, OR 1.60; 95% CI 0.73, 3.48) nor after controlling for potential confounders (OR 0.68; 95% CI 0.17, 2.77, OR 2.39; 95% CI 0.87, 6.55)." (PMID 35361818, 2022). "Of note, serum IL-4 levels were reduced, while IL-6, TNF, VEGF, and MCP-1 concentrations were increased, in patients with sarcopenia compared to those with no sarcopenia." (PMID 38001845, 2023). "The area under curve of the ROC analysis to discriminate participants with and those without sarcopenia was 0.65 (95% CI, 0.54-0.75) for TNF-α, 0.74 (95% CI, 0.65-0.84) for IL-1β, 0.80 (95% CI, 0.71-0.88) for IL-6 and 0.55 (95% CI, 0.44-0.66) for IL-15." (PMID 38032288, 2023). "The study found that, compared with those in non-sarcopenia patients, the serum levels of IL-6, IL-18, TNF-α, TNF-like weak inducing factor of apoptosis (TWEAK), and leptin were significantly increased in sarcopenia patients." (PMID 37584041, 2023). "Surprisingly, older adults with possible sarcopenia did not concurrently exhibit a higher level of IL-6 and TNF-α than non-sarcopenia subjects in our study." (PMID 36714126, 2022). "Comparisons of living habits, disease status, biochemical indexes, and levels of interleukin (IL)-4, IL-6, IL-8, IL-10, and tumor necrosis factor (TNF)-α in sarcopenia and non-sarcopenia participants were made in this study." (PMID 36160136, 2022). "Of note, elderly ED patients with sarcopenia did not exhibit higher concentrations of IL-6 and TNF-α, which indicated that possible sarcopenia did not correlate with systemic inflammation." (PMID 36714126, 2022).